HIF1A (hypoxia inducible factor 1 subunit alpha)
Diseases named in the same sentence as HIF1A in open-access papers (continued):
Sharing a sentence is not in itself a finding about the gene and the disease.
ovarian carcinoma (continued). "Since EMT has been shown to promote invasive migration of cancer cells, our results would suggest that the stimulation of HIF1α by LPA is required for such invasive migration of ovarian cancer cells." (PMID 27166196, 2016). "In the present study, we demonstrate the role of LPA in the potent activation of HIF1α in ovarian cancer cells." (PMID 27166196, 2016). "Nonetheless, our report demonstrates that Gαi2 and Src are needed for HIF1α activation in hypoxic conditions, indicating that inhibition of this pathway can suppress hypoxia-induced resistance in ovarian cancer patients." (PMID 27166196, 2016). "Our results indicated that LPA stimulated an increase in HIF1α in three different ovarian cancer cell lines, namely OVCAR5, OVCAR2, and OVCA429." (PMID 27166196, 2016). "In light of the recent findings that HIF1α plays a critical role of in ovarian cancer progression and malignancy, we sough to investigate the mechanism by which LPA stimulates the activity of HIF1α." (PMID 27166196, 2016). "HIF1α has been shown to play a critical role in ovarian cancer malignancy, especially ovarian cancer cells found in the hypoxic conditions of the peritoneal cavity." (PMID 27166196, 2016). "Using a transcription factor activation reporter array, which analyzes 45 distinct transcription factors, it has been observed that LPA observed robustly activates the transcription factor hypoxia-induced factor-1α (HIF1α) in SKOV3.ip ovarian cancer cells." (PMID 27166196, 2016). "Our results further demonstrate that the presence of LPA synergistically increases the expression levels of HIF1α through a Gαi2-dependent signaling pathway in hypoxic conditions, such as those found in the ascites fluid of ovarian cancer patients." (PMID 27166196, 2016). "Since the expression levels of HIF1α correlate with its activation, we first determined the expression levels of HIF1α following LPA stimulation in a panel of ovarian cancer cells." (PMID 27166196, 2016). "We further demonstrate that that the activation of LPA-Gαi2-Src-mediated signaling pathway induces EMT in ovarian cancer cells and subsequent invasive migration of ovarian cancer cells that can be inhibited by PX-478, a clinically tested inhibitor of HIF1α." (PMID 27166196, 2016). "Validation of the array analysis indicated that LPA stimulates a rapid increase in the levels of HIF1α in ovarian cancer cells, with an observed maximum level of HIF1α-induction by 4 hours." (PMID 27166196, 2016). "Together, our findings establish the functional role for LPA-Gαi2-Src stimulated HIF1α in promoting EMT phenotype in ovarian cancer cells involving the overexpression of Slug and increased invasive migration." (PMID 27166196, 2016). "In the present study, we for the first time confirmed that SENP1 inhibition can sensitize ovarian cancer cells to cisplatin in hypoxia by inhibiting HIF-1α." (PMID 26548925, 2015). "In an in vivo and in vitro study, up-expression of miR-199a and miR-125b inhibited tumor-induced angiogenesis associated with the decrease of HIF-1α and VEGF expression in ovarian cancer cells." (PMID 26065676, 2015). "In this study, we examined the expression of HIF-1α protein in ovarian cancer cells of SKOV3 by inhibiting or up-regulating SENP1 and found that SENP1 stabilized HIF-1α protein in hypoxia through desumoylation." (PMID 26548925, 2015). "Previous studies showed that the anticancer flavonoid compound kaempferol inhibited angiogenesis in ovarian cancer cells by downregulating HIF-1α expression." (PMID 25845666, 2015). "In this study, we identified that SENP1 positively regulated the expression of HIF-1α by deSUMOylation and weakened the sensitivity of hypoxic ovarian cancer cells to cisplatin." (PMID 26548925, 2015). "It has also been reported that the IGF system suppresses angiogenesis through the PI3K/HIF-1α/VEGF signaling pathways in a hypoxic microenvironment in ovarian cancer." (PMID 25663870, 2015).
ovarian carcinoma (continued). "Among the critical contributors to the invasive and metastatic capability of ovarian cancer cells is hypoxia of the tumor microenvironment, which mediates tumor cell invasion and metastasis through stabilization of hypoxia-inducible factor-1 alpha (HIF-1α)." (PMID 25197976, 2014). "Ovarian cancer is highly angiogenic, and our laboratory and others have correlated ovarian cancer progression with the expression of angiogenic signaling molecules, including hypoxia-inducible factor (HIF-1α) and vascular endothelial growth factor (VEGF)." (PMID 25163878, 2014). "To better understand the molecular mechanisms by which 20(S)-Rg3 blocks hypoxia-induced EMT in the ovarian cancer cells, we analyzed the expression of HIF-1α, a crucial regulator of EMT, at both the transcriptional and translational levels." (PMID 25197976, 2014). "One study in an ovarian cancer cell line revealed that hypoxia, via hypoxia-inducible factor-1a (HIF-1a), is able to induce TUBB3 expression." (PMID 24396456, 2014). "In the present study, we found that ROS accumulation in ovarian carcinoma cells upregulated HIF-1α expression and subsequent transcriptional induction of lysyl oxidase (LOX) which repressed E-cadherin." (PMID 25174950, 2014). "Collectively, these results suggest that 20(S)-Rg3 blocked hypoxia-induced EMT of the ovarian cancer cells by activating the PHD1- VHL- ubiquitin/proteasome pathway to facilitate HIF-1α degradation." (PMID 25197976, 2014). "In conclusion, it was demonstrated that Twist2 was expressed at significantly higher levels in ovarian carcinoma cells and in correlation with HIF-1α." (PMID 23946798, 2013). "But we found that miR-199a inhibited HIF-1α protein expression through HER2 and HER3 instead of directly targeting HIF-1α in ovarian cancer cells." (PMID 23437196, 2013). "An increasing amount of data shows that hypoxia-inducible factor-1α (HIF-1α) is an important biological marker in the evaluation of the prognosis of patients with ovarian carcinoma." (PMID 23946798, 2013). "Considering these results, further investigation into the interrelationship between Ets-1, Nrf2, and HIF-1α in ovarian cancer cells is warranted." (PMID 24238102, 2013). "Overexpression of miR-199a and miR-125b inhibited tumor-induced angiogenesis associated with the decrease of HIF-1α and VEGF expression in ovarian cancer cells." (PMID 23437196, 2013). "For instance, hypoxia increases the survival and chemoresistance of ovarian CSC/TICs isolated from ovarian cancer cell lines through the induction of c-kit expression mediated by HIF-1α." (PMID 23528891, 2013). "A series of matched tissue sections from formalin-fixed and paraffin-embedded human primary ovarian cancer and normal ovarian tissues were examined via immunohistochemical analysis to assess the correlation between Twist2 and HIF-1α expression." (PMID 23946798, 2013). "Overall, out of the 30 cases of ovarian tissue (including the primary ovarian cancer and normal ovarian tissues), 16 cases (53%) showed Twist2 positive expression and 18 cases (60%) showed HIF-1α-positive expression." (PMID 23946798, 2013). "Under oxidative stress, HIF-1α was decreased in response to SAS treatment only in cells that overexpress Ets-1 suggesting that GSH depletion regulates HIF-1α levels in ovarian cancer cells." (PMID 24238102, 2013). "To study how hypoxia affects LOX and HIF-1α expression, we exposed the ovarian cancer cell lines HO8910-PM, HO8910, COC1 and SKOV3 in 1% oxygen to mimic hypoxia condition." (PMID 23545606, 2013). "It has been reported that HIF-1α expression is increased in other ovarian cancer cell lines in response to hypoxia, which are largely in line with our present study." (PMID 22642602, 2012). "Our results also provide evidence that DIM inhibits the invasion of ovarian cancer cells and angiogenesis by inhibiting HIF-1α and VEGF, which are regulated by STAT3." (PMID 22280969, 2012).
ovarian carcinoma (continued). "By analyzing HIF-1α expression using western blotting we showed that treatment with bevacizumab increases intratumoral hypoxia in metastasis models of ovarian cancer." (PMID 22357313, 2012). "Inhibition of p38α activity by the specific inhibitor SB202190 impairs the expression of genes sustaining the altered metabolism of ovarian cancer cell lines and induces a shift from HIF1α- to FoxO3A-dependent transcription." (PMID 22481926, 2012). "Tumor xenografts obtained from stable HIF1α-silenced ovarian cancer cells show increased cell death and necrosis, and the expression levels of HIF1α have been proposed as an independent prognostic factor in patients with epithelial ovarian tumors." (PMID 22481926, 2012). "To find a proper model to examine the effect of triptolide on HIF-1α protein, we first tested the sensitivity of human ovarian cancer SKOV-3 cells to this compound because the cells are highly sensitive, both in vitro and in vivo, to triptolide analogues." (PMID 20932347, 2010). "In vitro, the effects of ABZ on HIF-1α levels in human ovarian cancer cells (OVCAR-3) were investigated using hypoxic chamber or desferrioxamine (DFO) induced-hypoxia." (PMID 20398289, 2010). "HIF-1α protein expression in ovarian cancer was first investigated using immunohistochemistry (IHC) by Zhong." (PMID 19014607, 2008). "Different histological types of ovarian carcinoma were used in his study, and HIF-1α immunostaining was observed in only 12 of the 48 cases of stages I and II (25%)." (PMID 19014607, 2008). "Similarly to the results shown in this study, the VEGFA expression was higher in cancer-affected tissue, whereas the HIF1A protein was at a lower level in malignant ovarian tumors." (PMID 39888575, 2026). "This treatment resulted in a significant increase of ROS and HIF-1α in all ovarian cancer cells, suggesting that ovarian cancer cells generate an oxidative stress response to counteract olaparib treatment, potentially through changes in the metabolism of mitochondria." (PMID 39625235, 2025). "Various strategies, such as pharmacological inhibitors, antioxidant therapy, anti-inflammatory agents, nanoparticle-based drug delivery, and lifestyle modifications, have been identified as potential interventions to reduce HIF-1α-driven ovarian cancer progression and infertility." (PMID 40136686, 2025). "Selective utilization of SHMT2 alternative promoter by HIF1α and TFE3 resulted in SHMT2 isoform expression shift, which might be implicated in adaptation of ovarian cancer cells under metabolic stress." (PMID 40097394, 2025). "In hypoxic ovarian cancer cells, HIF-1α silencing decreases VEGF expression." (PMID 39967908, 2025). "Disruption of HIF-1α function inhibits ovarian cancer metastasis." (PMID 40136686, 2025). "Elevated levels of NOX-derived ROS in ovarian cancer cells activate the HIF-1α/VEGF pathway." (PMID 40847302, 2025). "Inflammation represents a significant factor modulated by HIF-1α in ovarian cancer." (PMID 40136686, 2025). "Anti-inflammatory agents may serve as a potential therapeutic approach for targeting HIF-1α in the control of ovarian cancer and the management of female infertility." (PMID 40136686, 2025). "Salt-inducible kinase 2 (SIK2) may promote MR of glucose through the PI3K/AKT/HIF-1α pathway and Drp1-mediated mitochondrial fission in ovarian cancer." (PMID 39588377, 2024). "Our findings suggest that targeting CRABP2 and HIF1α may be a promising strategy for overcoming chemotherapy resistance in ovarian cancer." (PMID 38195606, 2024). "Based on the previous experimental results, we wanted to know whether CRABP2 could affect the metabolism of ovarian cancer cells by regulating the expression of HIF1α, ultimately affecting the sensitivity of tumor cells to chemotherapy drugs." (PMID 38195606, 2024).
ovarian carcinoma (continued). "Furthermore, the positive correlation between CRABP2 and HIF1α protein expression in ovarian cancer tissues, particularly in chemotherapy-insensitive tumors, further supports the clinical relevance of this interaction." (PMID 38195606, 2024). "Mechanistically, we found that abnormal expression of CRABP2 can cause abnormal activity of the RA signaling pathway, leading to upregulation of HIF1α expression and increased overall metabolic activity in cells, ultimately resulting in ovarian cancer cell drug resistance." (PMID 38195606, 2024). "In addition, we found a positive correlation between the protein expression levels of CRABP2 and HIF1α in ovarian cancer tissues, and the correlation was stronger in chemotherapy-insensitive ovarian cancer tissues." (PMID 38195606, 2024). "Thus, this study demonstrates that NQO1 plays a key role in HIF-1α stabilization, and a dual treatment with dicoumarol and sorafenib can significatively increase sorafenib sensitivity in ovarian cancer cells." (PMID 37175546, 2023). "PDK1 is upregulated by HIF1α through the HIF1α-RTK pathway in ovarian cancer." (PMID 37277821, 2023). "Thus, SIK2 impairs glucose metabolism and increases mitochondrial fission in ovarian cancer cells by activating the PI3K/AKT/HIF-1a pathway." (PMID 37508561, 2023). "The role of HIF-1α, which cobalt chloride is used to induce, in ovarian cancer cells may involve a reduction in E-cadherin, as demonstrated in two human ovarian cancer cell lines (SKOV3 and OVCAR5)." (PMID 36611913, 2022). "However, the decreased glycolysis by metformin was abrogated by HIF-1α over-expression in ovarian cancer cells." (PMID 35101076, 2022). "However, in non-small cell lung cancer cells and ES-2 ovarian cancer cells, HIF-1α aggravated ferroptotic cell death." (PMID 35906211, 2022). "Finally, we investigated how TRPM7 silencing decreased HIF-1α protein levels in ovarian cancer cells." (PMID 35101076, 2022). "In vitro findings suggest that nuclear HIF1A has prognostic importance in ovarian cancer, and EPAS1 may play a crucial role in the carcinogenesis and progression of ovarian malignancies." (PMID 36230822, 2022). "Conceivably, these findings may uncover the regulation of the TRPM7/AMPK/HIF-1α axis on the glucose metabolic reprogramming in ovarian cancer." (PMID 35101076, 2022). "Moreover, enhanced AMPK activation inhibited glycolysis, which was abrogated by HIF-1α over-expression in ovarian cancer cells." (PMID 35101076, 2022). "Thus, HIF-1α, c-Myc and Src stimulated through norepinephrine modulate hTERT expression in ovarian cancer to promote progression and invasion." (PMID 35974340, 2022). "Furthermore, similar fundings were also reported in ovarian cancer and other tumors, implying the malgenic roles of HIF-1α in the progression of tumors." (PMID 36091021, 2022). "For example, lysophosphatidic acid (LPA) secreted from ovarian cancer cells was shown to induce transcription of hypoxia-inducible factor 1-alpha (HIF1α) by binding its receptor LPAR on activated fibroblasts, inducing these cells to gradually switch their metabolism toward glycolysis." (PMID 35892828, 2022). "Furthermore, silencing of HIF-1α downregulated AKT/mTOR in ovarian cancer cells, further demonstrating the interplay between these two pathways." (PMID 36230617, 2022). "Given that glycolysis inhibition is associated with HIF-1α degradation we hypothesize that TRPM7 activation may modulate the HIF-1α/AMPK signaling to regulate glucose metabolism and promote ovarian cancer cell proliferation." (PMID 35101076, 2022).
ovarian carcinoma (continued). "LDHA is a HIF1α-targeted glycolytic gene, which is upregulated in ovarian cancer cells." (PMID 35498135, 2022). "These outcomes may indicate that the glucose metabolic reprogramming in ovarian cancer is regulated by the TRPM7/AMPK/HIF-1α axis." (PMID 36844925, 2022). "Meanwhile, the ability of the HIF-1α expression plasmid to enhance the TLR4 expression and the ability of HIF-1α shRNA to inhibit the TLR4 expression provided additional evidence to sustain the role of HIF-1α on regulating the expression of TLR4 in ovarian cancer cells." (PMID 35464826, 2022). "Furthermore, treatment with metformin to enhance AMPK activation promoted the shifting from glycolysis to OXPHOS in ovarian cancer cells, which was abrogated by HIF-1α over-expression." (PMID 35101076, 2022). "Targeting HIF-1α is considered a promising approach to improve ovarian cancer outcomes." (PMID 33802884, 2021). "Collectively, our results show for the first time that LPA induces DDR2 expression and consequent ovarian cancer cell invasion through the HIF-1α and Twist1 signaling axes, reinforcing the significance of LPA and the transactivation between GPCR and RTK in ovarian cancer progression." (PMID 34065317, 2021). "High HIF-1α expression is a prognostic factor in ovarian cancer." (PMID 33802884, 2021). "In order to explore the role of NOX4 and HIF-1α in the radiation therapy of ovarian cancer, OVCAR3 cells were transfected with shNOX4 or control shNC vector; at 48 h after transfection, cells were irradiated with 6MV X-ray linear accelerator at doses of 0 Gy, 2 Gy, 4 Gy and 6 Gy." (PMID 34209278, 2021). "Furthermore, knockout HIF-1α by CRISPR-cas9 resulted in significant downregulation of NOX4 in A2780 ovarian cancer cells." (PMID 34209278, 2021). "Taken together, TSE1 might be a potential candidate compound for improving platinum-resistant ovarian cancer treatment via Dll4/Jagged1-Notch1-Akt-HIF-1α axis." (PMID 33802884, 2021). "It has been reported to inhibit ovarian cancer cell growth by inhibiting the secretion of the primary angiogenesis mediators, Akt, hypoxia-inducible factor 1-alpha (HIF-1α), nuclear factor kappa-light-chain-enhancer of activated B cells (NF-κB), and vascular endothelial growth factor (VEGF)." (PMID 34830339, 2021). "Furthermore, knockdown of VHL by siVHL transfection also efficiently blocked shMIR210HG-mediated HIF-1α reduction in ovarian cancer cells." (PMID 34900667, 2021). "Our study suggests that hypoxia-induced MIR210HG promotes cancer progression by inhibiting HIF-1α degradation in ovarian cancer, which could be a therapeutic target for ovarian cancer." (PMID 34900667, 2021). "Additionally, the suppression of HIF-1α by baicalein contributed to its reduction of cell viability in ovarian cancer (OVCAR-3 and CP-70) cell lines." (PMID 33401572, 2021). "In addition, IL-6 also enhanced the chemoresistance of ovarian cancer cells against cisplatin through the IL-6/STAT3/HIF-1α loop in vitro and in vivo." (PMID 33868231, 2021). "Moreover, the essential role of HIF-1α was proposed in LPA-induced ovarian cancer EMT through Gi and Src." (PMID 34065317, 2021). "In our previous study, we found that ROS levels were significantly increased in ovarian cancer cells compared with normal cells, which regulated hypoxia-inducible factor 1α (HIF-1α) and vascular endothelial growth factor (VEGF) expression, and induced angiogenesis and tumor growth." (PMID 34209278, 2021). "LPA was shown to induce HIF-1α in several cancers, including ovarian cancer." (PMID 34065317, 2021). "As a crucial metabolic reprogramming factor, HIF-1α may be involved in the progression of a borderline ovarian tumor to an epithelial ovarian cancer, which entails hypoxia-induced invasiveness and migration." (PMID 34329303, 2021). "In ovarian cancer cells, resveratrol inhibits the expression of HIF-1α." (PMID 34829589, 2021).